PARP1 (poly(ADP-ribose) polymerase 1)
Diseases named in the same sentence as PARP1 in open-access papers (continued):
Sharing a sentence is not in itself a finding about the gene and the disease.
cancer (continued). "The PARP-1 Val762Ala (rs1136410) polymorphism has been implicated in cancer susceptibility." (PMID 24392019, 2013). "Several oncogenic viruses also possess high affinity PARP1 binding motifs in their genome, suggesting that they may act on PARP1 in a similar manner to increase host risk for developing cancer." (PMID 24970148, 2012). "The PARP-1 Val762Ala(GTG/GCG) polymorphism has been implicated in cancer susceptibility." (PMID 22624032, 2012). "Various human cancers display an overexpression of PARP1, which may be a reflection of the increased levels of DNA damage in cancer cells, often caused by oncogene-induced replication stress." (PMID 24970153, 2012). "Hence, these results offer support for the use of combined inhibition of PARP-1 and telomerase as a strategy to minimise the problems associated with long-term telomerase inhibition in cancer therapeutics." (PMID 20678253, 2010). "The recent discovery that PARP-1 inhibitors kill BRCA1/2 deficient cells with a high level of specificity subsequently opens up a potential therapy which looks very hopeful for BRCA1 cancer patients." (PMID 20961453, 2010). "Hence, these results offer support for the use of co-inhibition of PARP-1 and telomerase as a strategy to overcome the limitations associated with telomerase inhibition alone for cancer therapy." (PMID 20678253, 2010). "The association of S100 proteins with inflammatory and neoplastic disorders together with the role of PARP-1 in stress response and tumorgenesis might indicate the link between S100 and inflammation-associated cancer." (PMID 17187679, 2006). "Therefore, it has been hypothesized that selectively inhibiting PARP1 would reduce PARPi toxicity associated with PARP2 inhibition while improving synthetic lethality in HRD cancers and subsequently improving the efficacy of PARPi treatments." (PMID 40521389, 2025). "Even though our and others’ previous studies show that FEN1 deficiency/inhibition and PARP1 inhibition synergistically kill cancer cells, our new observations suggest that the efficacy of combined FEN1 inhibition and PARP1 inhibition in killing cancer cells may at least partly depend on LIG1 status." (PMID 41280084, 2025). "However, if the damage is extensive or the PARP-1 function is compromised, the repair process may be insufficient, leading to genomic instability and an increased risk of cancer development." (PMID 40282301, 2025). "Moreover, our newly developed method could be utilized to assess the effects of clinical PARPi on subnuclear PARP1 localization in cancer-relevant model systems, such as BRCA-deficient cells or cell lines with other homologous recombination deficiencies." (PMID 39036969, 2024). "Hence, we aimed to investigate whether cancers with low PSIP1 levels are sensitive to PARP1 inhibitors or illudin-S that cause transcription-coupled DNA damage." (PMID 38191578, 2024). "Therefore, the stabilization of PARP1 G4 could be a promising strategy for treating BRCA-deficient cancers." (PMID 36838818, 2023). "With the exception of monotherapy agents for BRCA-mutated cancers, PARP1 inhibitors can also be used as collaborators with radiotherapy/chemosensitizers, such as paclitaxel, bevacizumab and topoisomerase inhibitors in combination therapy for various cancer types." (PMID 36497058, 2022). "In addition, PARP1/2 themselves are critical for Mre11-dependent replication restart at stalled replication forks, and their inhibition by PARPi also causes genome instability and synthetic lethality in HR-deficient cancer cells." (PMID 35270034, 2022). "Moreover, combination of RAD52 and PARP1 inhibitors could improve the response to treatment in HR-deficient cancers." (PMID 34201502, 2021). "This, opens up the possibility that KMT2C-associated cancers may be targeted by PARP1/2 inhibitors." (PMID 33381456, 2020). "However, the roles of PARP‐1 rs1136410 C>T on cancer risk vary from different studies." (PMID 33108038, 2020).
cancer (continued). "However, the suggested mechanisms of PARP1-dependent activity of PJ34 in cancer cells are inconsistent with its exclusive PARP1 independent cytotoxic activity in human cancer cells at a higher concentration range than that causing PARP1 inhibition." (PMID 32575437, 2020). "The use of PARP1 inhibitor could potentially improve treatment outcomes for RB-deficient cancers." (PMID 33271982, 2020). "Moreover, cancers carrying mutations in these genes could be more sensitive to PARP1 inhibition, because our data suggest that their activity could efficiently modulate PARP1 activity." (PMID 31105872, 2019). "In fact, while DNA repair failure consequent to PARP-1 abrogation might increase mutations frequency promoting tumorigenesis, inhibition of inflammatory pathway may be protective as inflammation is now recognized as a cancer hallmark." (PMID 31877876, 2019). "Therefore, genetic variants of PARP1 that contribute to PARP1 activity may be a risk factor for cancer development and progression." (PMID 30183716, 2018). "Therefore, cancer cells harboring HR deficiencies are exceptionally sensitive to PARP1-i." (PMID 28427225, 2017). "Finally, further exploring the functions of Parp1 in stem cells and in cell reprogramming will reveal the underlying mechanisms of tumor progression and help to develop a suitable treatment strategy for cancer therapy." (PMID 26184161, 2015). "However, this potential connection to OCDLs and inflammation may provide a wider therapeutic application for PARP-1 inhibitors as a potential preventative agent in cancers highly associated with inflammatory phenotypes." (PMID 24202328, 2013). "Additionally, it may provide a feasible avenue for the novel use of PARP-1 inhibitors to prevent cancer outside that of BRCA-associated tumors." (PMID 24202328, 2013). "Furthermore, as a PARP1 inhibitor, bufalin might be effective in those cancer cells with BRCA1/2 deficiencies, a concept which warrants further investigation." (PMID 23762475, 2013). "Poly(ADP-ribose) polymerase activity can be higher in cancer than in adjacent normal tissue, but cancer predisposition is reported to be greater in individuals with a single-nucleotide polymorphism (SNP) V762A (T2444C) in the catalytic domain that reduces PARP-1 activity." (PMID 19568233, 2009). "A BRD4 degrader (ZBC260) achieved potent BRD4 depletion at low nanomolar doses, suppressed FOXM1/MYC and HR gene expression, enhanced PARP1 trapping, and produced strong synergy with olaparib, including in patient-derived cancer cells." (PMID 41820523, 2026). "Altogether, this data shifts the understanding of the role of PARP1 in MMEJ and DNA repair pathway choice and further strengthens a rationale for PARPi/MMEJi combinatorial drug treatment in HR-deficient cancers." (PMID 41495903, 2026). "It was shown that trabectedin, niacinamide, niraparib, talazoparib tosylate, olaparib, rucaparib camsylate, talazoparib, and rucaparib were capable of modulating PARP1 in cancer cells." (PMID 41561226, 2026). "PARP1/2 inhibitors (PARPi) are effective in cancer therapy due to their synthetic lethality in cells with defects in DNA double-strand break repair (DSBR)." (PMID 42234580, 2026). "We opted for the PARP1/2 inhibitor olaparib for rescue studies, given its established clinical application in cancer therapy." (PMID 41310943, 2026). "Target mapping implicated clinically relevant proteins such as carbonic anhydrase 2 (CA2), PARP1, and PPARA, associated with metabolic disorders, neurodegeneration, and cancer." (PMID 42221505, 2026). "Meanwhile, treatment with rosa and cisplatin either alone or in synergy reduced the PARP-1 expression and it was found that its inhibition promotes the death of the cancer cells." (PMID 40022036, 2025). "Together, these data suggest that PARP1 trapping, and not only its enzymatic inhibition, is a key driver for PARPi effectiveness in BRCA1m cancer cells." (PMID 41459749, 2025).
cancer (continued). "Previous studies have shown that inhibition of RNF114 E3 ligase activity by Nimbolide treatment can result in trapping of PARP1 and synthetic lethality in BRCA-mutated cancers, suggesting its E3 ligase role in tumor progress." (PMID 40092691, 2025). "Interaction between HES1, a downstream effector of Notch, and PARP-1 has been identified to finally induce apoptosis in B leukemic cells, as a protective mechanism against this type of cancer." (PMID 39858519, 2025). "PARP1 targeting has been successfully used in some cancers and is actively studied in many age-related diseases, including cancers and NDD." (PMID 39941940, 2025). "Dimeric structure of ZQJ29 facilitates dual targeting of PARP1 and the ferroptosis pathway, and amplifies ROS generation to synergistically drive ferroptosis in cancer cells." (PMID 40387570, 2025). "Poly(ADP‐ribose) polymerase‐1 (PARP‐1) is a multidomain enzyme essential for the DNA damage response; its inhibition can lead to cancer cell death." (PMID 41230800, 2025). "Cytoplasmic localization of PARP-1 has been described in cancer cells, although its functions are still unclear." (PMID 39858519, 2025). "Recurrent cancer cells are highly dependent on PARP1 activity for survival under treatment pressure." (PMID 40864763, 2025). "The elevation of cleaved PARP1 suggests that U-359 enhances the intrinsic apoptosis cascade, sensitizing cancer cells to chemotherapy-induced cell death." (PMID 40243608, 2025). "PARP‐1 is a key enzyme in the DNA damage response, and its inhibition induces cancer cell death via synthetic lethality." (PMID 41230800, 2025). "With the growing recognition that PARP-1 is likely the critical target for PARPi-induced synthetic lethality in HR defective cancers, there is intense interest in developing compounds with improved PARP1 selectivity." (PMID 40460119, 2025). "PARP inhibitors (PARPi) mostly act through PARP1 trapping, which stalls replication forks and causes synthetic lethality in HR-deficient tumours, such as BRCA1/2-defective cancers." (PMID 41188872, 2025). "Overexpression of PARP1 has been observed in various cancers, highlighting its clinical potential as a therapeutic target for human malignancies." (PMID 40713706, 2025). "Inhibition of PARP1 has emerged as a highly effective strategy for the clinical treatment of cancer." (PMID 40920657, 2025). "Since HELLS and PARP1 are known to be frequently overexpressed in many cancer types, we sought to determine if HELLS and PARP1 are co-expressed at the RNA and protein level by analyzing the TCGA and CPTAC web portals." (PMID 41297801, 2025). "Inhibiting PARP-1 leads to decreased DNA repair function and is considered an important mechanism for alleviating cisplatin resistance in cancer cells." (PMID 40577815, 2025). "With continuous optimization and refinement, it is anticipated that PARP-1-targeted probes can be developed into a precise and effective tool to benefit cancer patients." (PMID 40444043, 2025). "PARP1/2 inhibitors are FDA-approved for the treatment of several cancers, with the greatest activity against tumors with homologous recombination deficiency." (PMID 40681873, 2025). "Given the critical roles of PARP1 in cancer and DNA damage repair, PARP1 has emerged as a promising target in cancer therapy." (PMID 40713706, 2025). "Subsequently, the FDA has approved several others, including Niraparib, Rucaparib, and Talazoparib, highlighting the critical role of PARP‐1 inhibitors in cancer treatment." (PMID 40290046, 2025). "This reduction was associated with increased cytotoxic activity against cancer cells, as indicated by increased apoptotic markers such as Cleaved Caspase‐3 and poly (ADP‐ribose) polymerase 1 (PARP1) in tumor tissue." (PMID 41221154, 2025).
cancer (continued). "Despite the widespread use of PARP1 inhibitors across various cancers, the combined effects of PARP1 inhibitors and PIM‐2 inhibitors in enhancing DNA damage have not been fully explored." (PMID 40557764, 2025). "All these reports led to the therapeutic targeting of PARP-1 in CSCs as an efficient strategy to treat cancer." (PMID 39858519, 2025). "This restoration of 5hmC has been shown to enhance PARP1 trapping, thereby re-sensitizing chemoresistant BRCA mutated cancer cells to PARP inhibition." (PMID 41243111, 2025). "Our previous work demonstrated that PARP‐1 inhibition by PJ‐34 induced cell death of Ets‐1‐expressing cancer cells." (PMID 39778077, 2025). "In a previous study, we revealed that poly(ADP‐ribose) polymerase‐1 (PARP‐1) inhibition by PJ‐34 results in Ets‐1 level increase in cells, which is related with cell death of Ets‐1‐expressing cancer cells." (PMID 39778077, 2025). "We detected increased levels of the cleaved, active fragment of caspase 3 in the tumors of the treated group, along with activation through cleavage of its downstream target PARP1, indicative of apoptotic cell death and cancer cell elimination." (PMID 40429884, 2025). "PARP1 inhibitors are used to block DNA repair leading to catastrophic DNA damage in cancer cells and have become an effective treatment adjuvant." (PMID 41005313, 2025). "By modulating the trapping capabilities of saruparib and veliparib, respectively potent and weak PARP1 trappers, our results indicate that PARP1 trapping is a key component of PARPi effectiveness in BRCA1m cancer cells." (PMID 41459749, 2025). "Related to the synthetic lethal DNA damage elicited in homologous recombination-defective cancer cells, many clinical PARPi can trap PARP1 and PARP2 on DNA as part of their anticancer mechanism of action." (PMID 40021124, 2025). "Both the percentage of cancer cells positive to caspase 3 activation and the overall levels of caspase 3 cleavage increased, as were the cleavage and deactivation of PARP1." (PMID 40429884, 2025). "This narrative review comprehensively summarizes the central role of PARP1 in DNA damage repair and critically examines its promise as a target for radiosensitization in cancer radiotherapy." (PMID 41367875, 2025). "Although both isomers bind to this enzyme, only cis-resveratrol appears to induce a structural modification that promotes interaction with poly-ADP-ribose polymerase 1 (PARP1), a key enzyme in cancer biology." (PMID 39942639, 2025). "It has been demonstrated that NUPR1 binds to poly [ADP-ribose] polymerase 1 (PARP1) and inhibits the activity of PARP1 in cancer cells." (PMID 39991577, 2025). "A model has been proposed to estimate R-loop levels and their prognostic value in cancer RNA-sequencing datasets, and PARP1 activation at R-loops has been suggested as a potential predictive biomarker for sensitivity to PARP and ATR inhibition." (PMID 41378389, 2025). "Numerous studies have demonstrated that PARP1 expression is significantly upregulated in various cancer types, including breast cancer, colorectal cancer, prostate cancer, and glioma." (PMID 40864763, 2025). "PARP-1 inhibitors are used clinically for cancer treatment and are being currently targeted for therapeutic treatment of NCDs." (PMID 40722879, 2025). "Many available PARP inhibitors (PARPi) are used in clinics, but many are inducing resistance over time, and it has been shown that cancer cells use upregulation of PARP1 as a mechanism to become resistant to PARPi." (PMID 41155228, 2025). "Hyperactivity of PARP1 in cancer cells promotes survival by repairing chemotherapy- or radiation-induced DNA damage, contributing to drug resistance." (PMID 41304924, 2025).
cancer (continued). "Here, we used SUM149PT BRCA1m cells as a model for such cancers and confirmed that PARP1 is dispensable for the survival of these cells." (PMID 41459749, 2025). "Upon inhibition of PARP1 activity, cancer cell proliferation was significantly impeded, levels of reactive oxygen species (ROS) were elevated, and DNA double-strand breaks were exacerbated." (PMID 41219748, 2025). "Our study establishes FANCA genetic alterations in cancer as a promising selection criterion for PARP1 inhibitor treatment." (PMID 40630542, 2025). "The notion that PARP1 trapping is a key mechanism driving the effectiveness of PARPi in BRCAm cancer cells is well-supported by the scientific literature but has more recently been questioned." (PMID 41459749, 2025). "Inhibition of PARP‐1 leads to inadequate function of the DDR repair system and inhibits replication in breast cancer genes 1 and 2 (BRCA1/2) protein‐deficient cancer cells, a concept known as “synthetic lethality”." (PMID 39945311, 2025). "On the one hand, inhibition of the PARylation activity of PARP1 impacts on DNA repair while on the other hand, PARP1 trapping both contributes to the inhibition of DNA repair and creates DNA lesions resulting in increased cytotoxicity in HRR-deficient cancers." (PMID 41459749, 2025). "Niraparib is a PARP1 and PARP2 inhibitor that has been approved for maintenance therapy in patients with recurrent cancers, particularly those exhibiting HR deficiency (HRD)." (PMID 41049266, 2025). "PARP1 inhibition has a potential effect during cancer treatment via trapping the PARP1 molecule to DNA damaged site thus, more cytotoxicity." (PMID 40022036, 2025). "PARP1 inhibition not only suppresses cell proliferation but also sensitizes cancer cells to DNA-damaging chemotherapy, suggesting the potential for combined therapies using PARPis and chemotherapeutic drugs." (PMID 40134437, 2025). "In this context, PARP1 inhibition appears to be a promising therapeutic strategy in cancer treatment, particularly in HNSCC." (PMID 40864763, 2025). "These next-generation PARP1-selective inhibitors hold significant promises for improving the survival and outcomes of cancer patients." (PMID 40521389, 2025). "Genetic inhibition of NUPR1 induces PARP1 over-activation and decreases ATP production and cell viability in cancer cells." (PMID 39991577, 2025). "In 2021, a pan-cancer study highlighted the significance of PARP1 alterations as cancer predictive biomarkers for immunotherapy, and its expression levels were correlated with the status of immunotherapy-associated signatures in several tumors." (PMID 38571962, 2024). "PARP1 is a widely targeted molecule in cancer treatment and, beyond its role in DNA repair, it participates in transcriptional regulation by recruiting chromatin remodeling complexes to modulate DNA accessibility for RNA polymerases." (PMID 38893160, 2024). "The study reported that microarray analysis of PARP‐1 gene expression in 8000 samples indicated that PARP‐1 expression was higher in several types of cancers than that in normal tissues." (PMID 38652105, 2024). "PARP1 inhibitors have been primarily used for cancer therapy because they can prevent the activation of DNA repair mechanisms and produce the death of neoplastic cells." (PMID 38397799, 2024). "IHC on patient and murine tissue revealed similar patterns of increasing PARP1 expression in presence of dysplasia and cancer." (PMID 38383387, 2024). "Recently, particular attention has been paid to Poly-ADP-Ribose Polymerase 1 (PARP-1), due to its implication in the development and progress of cancer." (PMID 38255943, 2024). "Western blot analysis revealed a marked increase in BAX and PARP1 expression in cancer cells treated with anlotinib alone or in combination with DDP, accompanied by a decrease in BCL2 expression." (PMID 39508048, 2024). "Absent the DNA trapping effect, 180055 demonstrated substantial PARP1 degradation in breast, ovarian, and other cancer cell lines." (PMID 39695097, 2024).